NEIL1 (nei like DNA glycosylase 1)
Description:
Involved in base excision repair of DNA damaged by oxidation or by mutagenic agents. Acts as a DNA glycosylase that recognizes and removes damaged bases. Has a preference for oxidized pyrimidines, such as thymine glycol, formamidopyrimidine (Fapy) and 5-hydroxyuracil. Has marginal activity towards 8-oxoguanine. Has AP (apurinic/apyrimidinic) lyase activity and introduces nicks in the DNA strand. Cleaves the DNA backbone by beta-delta elimination to generate a single-strand break at the site of the removed base with both 3'- and 5'-phosphates. Has DNA glycosylase/lyase activity towards mismatched uracil and thymine, in particular in U:C and T:C mismatches. Specifically binds 5-hydroxymethylcytosine (5hmC), suggesting that it acts as a specific reader of 5hmC.
Synonyms: FLJ22402; hFPG1; NEI1; FPG1
Tractability: Small molecule: a high-quality ligand is known.
Target class: Enzyme; Hydrolase
Gene: Protein-coding gene on chromosome 15 (75,346,878 to 75,357,115, forward strand). Ensembl gene ENSG00000140398.
Subcellular location: Cytoplasm, cytoskeleton, microtubule organizing center, centrosome; Nucleus; Chromosome
Subcellular location (Human Protein Atlas): Nucleoplasm
Pathways (Reactome):
DNA Repair: APEX1-Independent Resolution of AP Sites via the Single Nucleotide Replacement Pathway; Cleavage of the damaged pyrimidine; Recognition and association of DNA glycosylase with site containing an affected pyrimidine
Disease: Defective Base Excision Repair Associated with NEIL1
Gene Ontology:
Molecular function: hydrolase activity, acting on glycosyl bonds; protein binding; DNA N-glycosylase activity; DNA-(apurinic or apyrimidinic site) endonuclease activity; class I DNA-(apurinic or apyrimidinic site) endonuclease activity; damaged DNA binding; hydrolase activity, hydrolyzing N-glycosyl compounds; lyase activity; nucleic acid binding; zinc ion binding
Biological process: base-excision repair; base-excision repair, gap-filling; depyrimidination; DNA repair
Cellular component: cytoplasm; nucleoplasm; nucleus; cytosol; centrosome; chromosome
Genetic constraint (gnomAD): Loss-of-function variants: 31 observed, 45.26 expected, observed/expected ratio (o/e) 0.68, 90% interval 0.51 to 0.92. The upper end of that interval is the gene's LOEUF score, 0.92, which puts it in group 3 of 6, group 1 being the genes least tolerant of losing a copy. Missense variants: 549 observed, 530.88 expected, observed/expected ratio (o/e) 1.03, 90% interval 0.96 to 1.11. Synonymous variants: 254 observed, 216.18 expected, observed/expected ratio (o/e) 1.17, 90% interval 1.06 to 1.3.
Homologues: Orthologues: chimpanzee NEIL1 (99% identical), macaque NEIL1 (94% identical), pig NEIL1 (83% identical), mouse Neil1 (79% identical), rat Neil1 (78% identical), guinea pig NEIL1 (76% identical), dog NEIL1 (57% identical), tropical clawed frog neil1 (51% identical), zebrafish neil1 (48% identical). Paralogues in human: NEIL3 (16% identical), NEIL2 (16% identical).
Diseases named in the same sentence as NEIL1 in open-access papers:
NEIL1 is named in the same sentence as 74 diseases in open-access papers, as found by Europe PMC text mining. Sharing a sentence is not in itself a finding about the gene and the disease. The quoted sentences say what the papers report.
Obesity (10 papers, 2012 to 2025). Accumulation of substantial excess body fat. "Defects in NEIL1 have been associated with increased risks of cancer, diabetes and obesity." (PMID 41030849, 2025). "NEIL1 deficiency can lead to metabolic syndrome, obesity and liver inflammation." (PMID 40033009, 2025). "Global deletion of either of two different glycosylases with varying substrate specificities, Nei-like endonuclease 1 (NEIL1) or 8-oxoguanine DNA glycosylase-1 (OGG1), both predispose mice to diet-induced obesity (DIO)." (PMID 34604220, 2021). "The absence of Neil1 potentially lowers the threshold for resistance to cellular oxidative stress in Neil1−/− mice, increasing their susceptibility to obesity and its associated complications." (PMID 40033009, 2025). "While we did not observe any changes in Neil1 expression during the adipogenic process, a similar obesity susceptibility phenotype has been reported in mice lacking NEIL1." (PMID 33503804, 2021). "Mice lacking the DNA glycosylase NEIL1, which acts on oxidized pyrimidines, show reduced DNA repair capacity only in mitochondria, but exhibit symptoms reminiscent of human metabolic syndrome such as severe obesity, dislipidemia and fatty liver disease." (PMID 23825659, 2013).
lung carcinoma (9 papers, 2016 to 2025). "Genetic analysis of NEIL1 gene polymorphisms in patients with lung cancer undergoing radiotherapy revealed an association between the rs7402844 GG genotype and a greater risk of RP grade ≥2 than the rs4462560 CC genotype." (PMID 40033009, 2025). "A total of 174 lung cancer patients treated with radiotherapy were genotyped for the NEIL1 genetic variants, rs4462560 and rs7402844." (PMID 40761744, 2025). "In summary, our study illustrates the effect of the NEIL1 gene SNPs on RP risk, that rs4462560 G>C and rs7402844 C>G is significantly associated with RP susceptibility in lung cancer patients after radiotherapy." (PMID 34105905, 2021). "Aberrant overexpression of ADAR1 in lung cancer is associated with poor prognosis in patients, as it enhances the editing frequencies of target transcripts such as Nei-like protein 1 (NEIL1) and miR-38177." (PMID 32346127, 2020). "In order to confirm whether the variant is disease causing or not, we further conducted a study to evaluate the association of NEIL1 SNPs with RP in lung cancer patients." (PMID 34105905, 2021). "Furthermore, our study expanded the tumor species and reached the same conclusion in lung cancer, suggesting that NEIL1 and its genetic polymorphisms play an important role in predicting tumor radiation damage." (PMID 34105905, 2021). "So, we hypothesis genetic variations in NEIL1 gene could affect the risk of RP in lung cancer patients following radiotherapy." (PMID 34105905, 2021). "Thus, NEIL1-mutant patients with lung cancer have a greater risk of RP than other patients do71." (PMID 40033009, 2025). "In short, NEIL1 (Nei Like DNA Glycosylase 1) is involved in DNA repair and is up-regulated in breast and lung cancer, reducing cancer cell death and promoting cancer progression." (PMID 39199284, 2024). "Genetic variations rs4462560 G>C and rs7402844 C>G in NEIL1 gene were genotyped in 174 lung cancer patients received radio(chemo)therapy." (PMID 34105905, 2021). "The deletion, silencing, and abnormal expression of NEIL1 may play important roles in lung cancer pathogenesis." (PMID 40761744, 2025). "Second, editing of NEIL1 and miR381 promoted the growth of A459 lung cancer cells." (PMID 35406793, 2022). "Lower doses of lycopene improve the levels of NEIL1, NEIL2, and NEIL3 in cigarette smoke-induced A549 human lung cancer epithelial cells." (PMID 40761744, 2025). "Taken together, NEIL1 and NEIL2 function as tumor suppressors and their abnormal expression can lead to the development of lung cancer and drug resistance." (PMID 40761744, 2025). "In lung cancer, ADAR1 was reported to exert growth-enhancing activity through mediating the A-to-I editing levels of coding region in NEIL1 (a DNA repair enzyme) and non-coding region in pre-miR381 RNA transcripts." (PMID 27863387, 2016). "Lycopene masked lung cancer proliferation by suppressing oxidative stress as well as by elevating 8‐oxo guanine DNA glycosylase (OGG1), connexin‐43 (Cx43), and Nei‐like DNA glycosylases (NEIL1, NEIL2, and NEIL3) expression." (PMID 40661795, 2025). "Herein, we examined two NEIL1 genetic variations in 174 lung cancer patients received radiotherapy with or without chemotherapy and investigated their association with the risk of RP." (PMID 34105905, 2021). "Unlike NEIL1 and NEIL2, NEIL3 functions as an oncogenic factor in lung cancer." (PMID 40761744, 2025).
metabolic syndrome (9 papers, 2012 to 2025). A cluster of metabolic risk factors for CARDIOVASCULAR DISEASES and TYPE 2 DIABETES MELLITUS. "Although metabolic syndrome has been reported in Neil1−/− mice, with an associated decrease in mtDNA integrity, correction of mitochondria-specific repair by transgenic NEIL1 expression has not been reported." (PMID 38779538, 2024). "Furthermore, analysis of Neil1−/− mice mitochondrial DNA revealed greater levels of ROS-induced DNA damage and loss than those in wild-type (WT) mice, highlighting that Neil1 plays a crucial role in preventing diseases associated with metabolic syndrome." (PMID 40033009, 2025). "Mice deficient of NEIL1 are viable but display metabolic syndrome and brain dysfunction." (PMID 31566562, 2019). "Interestingly, a deficiency of NEIL1 in knockout mouse models displays an obese phenotype associated with a metabolic syndrome." (PMID 27924031, 2017). "Furthermore, a deficiency of NEIL1 in knockout mouse models displays an obese phenotype associated with a metabolic syndrome, and loss of NEIL1 has been associated with the earliest symptoms of age-related neurodegenerative disorders such as Alzheimer's and Parkinson's diseases in humans." (PMID 27924031, 2017). "Neil1 mutants present metabolic syndrome and show impaired brain function and neuronal stress resistance in adults." (PMID 31566562, 2019). "Moreover, Neil1-mutant mice harbor increased mtDNA damage in liver tissue, which might be related to the metabolic syndrome observed in these mice." (PMID 31566562, 2019). "Since NEIL1 and OGG1 have very distinct substrate specificities in the repair of oxidized lesions, these similarities in phenotype with regard to the development of metabolic syndrome were completely unexpected." (PMID 23284747, 2012).
gastric cancer (7 papers, 2008 to 2025). A primary or metastatic malignant neoplasm involving the stomach. "Stomach tissue is particularly prone to oxidative damage and some somatic NEIL1 variants and germline polymorphisms have been found in gastric cancer patients indicating a possible role in stomach polyp formation." (PMID 36387175, 2022). "Recent studies have demonstrated the importance of NEIL1 in maintaining genomic integrity as mutations in NEIL1 have been associated with gastric cancer and colorectal adenomas." (PMID 23104860, 2012). "High NEIL1 expression, for example, may be associated with a poor prognosis in patients with gastric cancer." (PMID 40761744, 2025). "Furthermore, the low activity of NEIL1 caused by mutations and its decreased expression in gastric cancer may be associated with the pathogenesis of few gastric cancers." (PMID 40761744, 2025). "To confirm the possibility of NEIL1 epigenetic silencing, we treated two gastric cancer cell lines (MKN45 and MKN74) with the cytosine methylation inhibitor 5-aza-dC and measured the levels of NEIL1 expression using QRT-PCR." (PMID 27042257, 2016). "The DNA repair inhibitor, berzosertib, may inhibit the expression of NEIL1, thus limiting the proliferation of gastric cancer cells." (PMID 40761744, 2025). "NEIL1, a gene involved in DNA repair, showed lower expression levels in the tumours from deceased patients in our material and has been reported as down-regulated in gastric cancer." (PMID 18778486, 2008). "Among the fourteen A-to-I non-synonymous editing events, three ones have been experimentally dissected as pivotal modulators involving in tumorigenesis, including A1099G at AZIN1 in HCC, A725G at NEIL1 in glioblastoma and A722G at PODXL in gastric cancer." (PMID 36476255, 2022).
colorectal cancer (6 papers, 2006 to 2024). A primary or metastatic malignant neoplasm that affects the colon or rectum. "This study demonstrated that upregulation of NEIL1 enhances colorectal cancer initiation through the formation of an RNA polymerase II transcriptional complex with SATB2 and cMyc, which drives COL17A1 expression leading to cancer-associated immunosuppression." (PMID 38779538, 2024). "The latest research on human colorectal cancer (CRC) shows that silence of NEIL1 in two CRC (HCT116 and SW480) cell lines promoted cell apoptosis through the caspase‐9 signaling pathway." (PMID 34105905, 2021). "On the other hand, our literature search did not identify reports of germline PVs in EXO1 or NEIL1 in OC, although variants in these genes have been reported in the context of other hereditary cancers such as colorectal cancer." (PMID 36969007, 2023).
Alzheimer disease (3 papers, 2019 to 2024). A progressive, neurodegenerative disease characterized by loss of function and death of nerve cells in several areas of the brain leading to loss of cognitive function such as memory and language. "In humans, NEIL1 SNPs have been associated with late-onset Alzheimer’s disease, and NEIL1 gene expression is down-regulated in the lymphocytes of AD patients." (PMID 38397143, 2024). "Besides, the upregulated genes of both Neil1- and Neil2-deficient EBs + RA were significantly enriched for the pathway term ‘TYROBP causal network’, associated with late-onset Alzheimer’s disease." (PMID 31566562, 2019).
depression (3 papers, 2012 to 2023). "It has been suggested in previously studies that the C/C and allele C genotype of NEIL1 rs4462560 were negatively correlated with recurrent depression disorder (rDD) while genotype G/G and allele G of the same SNP were positively correlated with the disease." (PMID 34105905, 2021). "Furthermore, it was previously suggested that the SNP in NEIL1 modulates the risk of recurrent depressive disorder." (PMID 37511066, 2023). "Several studies have addressed the importance of NEIL1 in neurological conditions, such as CS, multiple sclerosis and depression." (PMID 23203191, 2012).
ischemia (3 papers, 2012 to 2025). A hypoperfusion of the BLOOD through an organ or tissue caused by a PATHOLOGIC CONSTRICTION or obstruction of its BLOOD VESSELS, or an absence of BLOOD CIRCULATION. "As already mentioned, NEIL1 has been linked to changes in oxygen levels and pathological conditions such as ischemia and stroke." (PMID 23203191, 2012). "In conclusion, NEIL1 seems to be important for the development of the brain, memory and learning, as well as in response to stroke and ischemia and it has been implicated in CS." (PMID 23203191, 2012). "A study on memory retention in Neil1-deficient mice used a water maze test and explored the protective role of Neil1 against ischemic injury in a focal ischemia/reperfusion stroke model." (PMID 40033009, 2025).
multiple myeloma (3 papers, 2022 to 2025). "In multiple myeloma cells, NEIL1 depletion contributes to melphalan resistance by downregulating the BER pathway, which facilitates the repair of the more toxic ICL." (PMID 40761744, 2025). "In melphalan-resistant multiple myeloma, NEIL1 expression is downregulated, leading to a greater propensity of cells to repair toxic ICL, thereby reducing G2/M phase arrest." (PMID 40761744, 2025). "NEIL1 is a vital and extensively edited ADAR1 target in multiple myeloma." (PMID 40761744, 2025).
Parkinson disease (3 papers, 2017 to 2022). A progressive degenerative disorder of the central nervous system characterized by loss of dopamine producing neurons in the substantia nigra and the presence of Lewy bodies in the substantia nigra and locus coeruleus. "NEIL1 also appears to play a role in reducing brain damage following ischemic stroke and loss of NEIL1 causes defects in olfactory function in mice, which are the earliest symptoms of age-related neurodegenerative disorders such as Alzheimer's and Parkinson's diseases in humans." (PMID 27924031, 2017).
Stroke (3 papers, 2012 to 2025). Sudden impairment of blood flow to a part of the brain due to occlusion or rupture of an artery to the brain. "NEIL1 deficiency causes neuroinflammation, which can lead to Parkinson’s disease (PD), stroke and defects in the development of cranial neural crest cells." (PMID 40033009, 2025). "This study highlights the key role of Neil1 in neuronal protection and memory, suggesting its potential as a therapeutic target for stroke and neurodegeneration." (PMID 40033009, 2025).
Anxiety (2 papers, 2021 to 2022). Intense feelings of nervousness, tension, or panic often arise in response to interpersonal stresses. "As the hippocampus is one of the critical brain areas involved in anxiety as well as learning and memory, we assessed the effect of NEIL1 and/or NEIL2 deficiencies on hippocampal DNA integrity." (PMID 34857879, 2021). "The current study revealed an altered behavioral phenotype in mice deficient in both the NEIL1 and NEIL2 DNA glycosylases, shown as increased locomotor activity in the OF test and the EZM, reduced anxiety in the EZM, and improved learning ability in the MWM test." (PMID 34857879, 2021). "Moreover, the knockout of DNA glycosylases NEIL1 and NEIL2 causes dysregulation of genes that are relevant for synaptic function in CA1 and leads to reduced anxiety and improved learning in these animals that is potentially linked to changes in GABAergic signalling." (PMID 35907861, 2022).
breast carcinoma (2 papers, 2022 to 2024). "We identified seven potential genes within breast cancer: NOL4, STAR, C8G, NEIL1, SLC46A3, FRMD6, and SCARF2." (PMID 39199284, 2024). "Through differential expression analysis and mutual information, we identified seven genes (NOL4, STAR, C8G, NEIL1, SLC46A3, FRMD6, and SCARF2) that are potential biomarkers in breast cancer." (PMID 39199284, 2024).
breast invasive carcinoma (2 papers, 2016 to 2022). "Reduction in NEIL1 expression was associated with a poorer outcome in patients with breast invasive carcinoma." (PMID 36497286, 2022). "Moreover, a multivariate analysis using the Cox proportional hazard model showed that a reduction in NEIL1 expression was associated with a significantly elevated risk of a poor survival outcome among patients with breast invasive carcinoma (HR: 2.194; 95% CI: 1.417–3.394; P = 0.0005)." (PMID 27042257, 2016). "Interestingly, in breast invasive carcinoma, which is one of the cancers that shows the epigenetic silencing of NEIL1, a reduction in NEIL1 expression was shown to be an independent predictor of a poor survival outcome." (PMID 27042257, 2016). "A Kaplan-Meier analysis showed that a reduction in NEIL1 expression was associated with a poorer outcome in patients with breast invasive carcinoma (P = 0.0025, log-rank test) but not in patients with the other 12 cancer types." (PMID 27042257, 2016). "We then showed that the reduced NEIL1 expression level observed in various cancers was due to epigenetic silencing by promoter hypermethylation and that such reduction was an independent predictor of a poor outcome among patients with breast invasive carcinoma." (PMID 27042257, 2016).
cervical carcinoma (2 papers, 2020 to 2025). A carcinoma arising from either the exocervical squamous epithelium or the endocervical glandular epithelium. "However, further studies are now required to investigate the relationship between genetic polymorphisms in the promoter region of NEIL1 and the risk of cervical carcinoma." (PMID 32198476, 2020). "Our results show that genetic polymorphisms in the introns of NEIL1 were not related to the occurrence of cervical carcinoma." (PMID 32198476, 2020). "In addition, the correlation between SNP loci in NEIL1 and NEIL2 and susceptibility to cervical carcinoma has not been studied so far." (PMID 32198476, 2020).
head and neck squamous cell carcinoma (2 papers, 2021 to 2025). A squamous cell carcinoma that arises from any of the following anatomic sites: lip and oral cavity, nasal cavity, paranasal sinuses, pharynx, larynx, and salivary glands. "NEIL1 expression is downregulated by the hypermethylation of the promoter region of NEIL1 in head and neck squamous cell carcinoma." (PMID 40761744, 2025).